IL6 (interleukin 6)
Diseases named in the same sentence as IL6 in open-access papers (continued):
Sharing a sentence is not in itself a finding about the gene and the disease.
myeloma (continued). "Additionally, this adhesion between cells increases IL-6 secretion by BMSCs, which in turn can increase the levels of VEGF that are secreted by myeloma cells (and vice-versa)." (PMID 32050631, 2020). "Indeed, high IL-6 has been shown to favor SOD2 expression in prostate, myeloma and brain cells affording protection against interventions inducing a cellular oxidative stress." (PMID 32365668, 2020). "This apoptotic effect was not counteracted by myeloma pro-survival cytokines such as IL-6 and insulin-like growth factor-I." (PMID 33384693, 2020). "Insulin growth factor-1 (IGF-1) is well known to play a critical role in driving myeloma cell survival through activation of distinct downstream signalling pathways independent of the cytokine IL-6." (PMID 32228485, 2020). "Within myeloma niche, after interaction with BM-derived mesenchymal stromal cells, TAMs acquire a secretory profile characterized by a great production of IL-6 and IL-10 and poor production of IL-12 and TNF-α, providing a suitable milieu for myeloma plasma cell growth." (PMID 33194767, 2020). "On the other hand, IL-6, VEGF and IGF-1, produced by BMECs, stimulate myeloma cells growth." (PMID 32050631, 2020). "While upregulation of anti-apoptotic genes is important for myeloma cell survival, it does not fully account for the survival benefits conferred by IL-6 through STAT3." (PMID 31130718, 2019). "Previous studies with myeloma cells have shown that anakinra can significantly reduce IL-6 levels but does not increase myeloma cell death." (PMID 31242947, 2019). "A greater proportion of myeloma cells do not generate IL-6 in vivo, but a minority that do produce autocrine IL-6 have been reported." (PMID 31185596, 2019). "The first published work regarding the regulation of miRNA expression in MM showed that interleukin 6 (IL6), the cytokine produced by bone marrow mesenchymal stem cells, induced changes in miRNA expression enhancing survival and drug resistance of myeloma cells." (PMID 30654527, 2019). "The mechanisms of ATE in myeloma patients are multifactorial and include increased levels of procoagulant factors such as von Willebrand factor and factor VIII and high levels of inflammatory cytokines such as interleukin 6 and tumor necrosis factors." (PMID 31741612, 2019). "It was shown that berberine suppresses interleukin 6 (IL6), a factor required for cell growth in multiple myeloma cells (U266), through negative regulation of the signal transducer and activator of transcription 3 (STAT3), and this induces inhibition of miR-21 expression." (PMID 30987378, 2019). "Unfortunately, overall, large randomized trials show no efficacy of IL-6 inhibitors in various cancers, particularly myeloma." (PMID 30671025, 2018). "Tumor-derived miR-146a may induce the activation of Notch1 in BMSCs stimulating them to secrete CCL2 and several cytokines including IL-8, IL-6, CXCL1, IP-10, and CCL5 that enhance myeloma cell viability and migration." (PMID 30154786, 2018). "We also showed that hypoxia-induced miR-210 might augment adhesion of MM cells to osteoblasts and mediate MSCs-differentiated osteoblasts by inducing expression of IL6 and TGF-β and releasing MVs from myeloma cells." (PMID 30108468, 2018). "The actions of IGF-1 on myeloma cells appear to be synergistic with those of IL-6 although mechanisms independent of IL-6 also have been demonstrated." (PMID 30544512, 2018). "Unlike multiple myeloma, where IL-6 was found to be crucial, GM-CSF was the essential stroma-derived factor for AML cell survival." (PMID 30406027, 2018). "In conclusion, we showed that IL-6 and lenalidomide, but not pomalidomide, are opponents in a myeloma-antigen specific T-cell model." (PMID 29228683, 2017). "Elevated IL-6 signaling may lead to heightened expression of Bcl-xL, which in concert with active STAT-3 signaling may induce multidrug resistance in myeloma." (PMID 29100463, 2017).
myeloma (continued). "A large body of evidence indicates that the physical interaction of myeloma cells and MMSCs (cell adherence) induces the non-malignant bystander cells to secrete cyto- and chemokines, such as IL-6, CD40, TRANCE and Ras, which collectively promote myeloma proliferation and survival." (PMID 29100463, 2017). "STAT3 protein binding at the EZH2 promoter was significantly increased in SGC7901 cells, and was increased 6.18-fold with IL-6 stimulation, which is consistent with the results of studies showing that EZH2 protein expression is induced by IL-6 in multiple myeloma cell lines." (PMID 27938379, 2016). "Importantly, the anti-MM activity of PTC-209 was upheld in the presence of major myeloma growth factors (IGF-1 and IL-6) as well as in co-culture with BMSCs." (PMID 26935956, 2016). "Importantly, the anti-MM activity was upheld in the presence of stromal support or myeloma growth factors insulin-like growth factor 1 (IGF-1) and interleukin 6 (IL-6)." (PMID 26935956, 2016). "There are two different sources of IL-6 in MM that promote tumor development and maintenance in vivo: autocrine IL-6 derived from myeloma cells and paracrine IL-6 derived from non-malignant cells of the BM niche." (PMID 27463014, 2016). "We hypothesized that, in myeloma patients, proinflammatory cytokine tumor necrosis factor-alpha (TNF-α) upregulates the production of interleukin-6 (IL-6), which then mediates increased secretion of MCP-1." (PMID 26925413, 2016). "Thus, this study provides important insights into CD45 isoforms’ signaling in multiple myeloma cells and suggests a different immunomodulatory role for CD45 isoforms in regulating IL-6-mediated proliferation." (PMID 25781885, 2015). "Our previous report also shows that inhibition of Lyn activity significantly blocks the proliferation-induced by IL-6 in CD45+ myeloma cells, but does not affect either STAT3 or ERK activation." (PMID 25781885, 2015). "Also, IL-6 can reverse CD33 expression by upregulating Myc and subsequently downregulating CCAAT/enhancer binding protein (CEBPA) expression in myeloma cells." (PMID 26508814, 2015). "First, we carefully evaluate whether the phosphorylation level of IL-6-mediated signaling molecules differed between CD45+ and CD45- myeloma cells." (PMID 25781885, 2015). "It has been established that interleukin-6 (IL-6) is the most important survival and growth factor in myeloma cells and regulated at least 3 pathways, namely JAK2/STAT3, MAPK/ERK, and PI3K/AKT, thus targeting IL-6-mediated signaling pathways is a promosing therapeutic strategy in MM." (PMID 25865044, 2015). "The Lyn-specific antisence and the phosphatase inhibitor together obstruct the IL-6-induced proliferation in CD45+ myeloma cells, but not in CD45- myeloma cells." (PMID 25781885, 2015). "Specially, other groups demonstrate the inhibition of ERK without interference with phosphorylation of STAT3, as well as the inhibition of arsenic trioxide on IL-6-induced STAT3 but not ERK activation in myeloma cells." (PMID 25781885, 2015). "Furthermore, interleukin-6 (IL-6) and insulin-like growth factor-1 (IGF-1) induce telomerase activity in myeloma cell lines." (PMID 25822740, 2015). "This factor increasesthe activity of interleukin-6 (IL-6), a growth andsurvival factor in MM, and plays an important rolein angiogenesis by stimulating secretion of vascularendothelial growth factor (VEGF) through the MEK/ERK pathway in myeloma cells." (PMID 24567933, 2014). "An HGF/Met/IL-11/IL-6/gp130/STAT3 cascade was found to be activated in PV clonal erythroblasts; activation of a similar autocrine HGF/IL-11/IL-6 cascade has been described in multiple myeloma and in solid tumours." (PMID 25119536, 2014). "Similarly, through the secretion of IL6, TNF-α, and BAFF, bone marrow stromal cells promote the survival of neoplastic plasma cells and also confer drug resistance in multiple myeloma." (PMID 25132836, 2014).
myeloma (continued). "At least in culture, addition of APRIL and IL-6 together did not support myeloma growth above that of the single factors added alone, suggesting that the two cytokines exhibit redundant effects for supporting myeloma growth." (PMID 25272036, 2014). "We were able to detect a significantly increased cell viability of myeloma cells after CCN1 incubation independent of IL-6 suggesting CCN1 as a microenvironment-derived pro-myeloma factor." (PMID 24965524, 2014). "The activation of MMP-9 is not regulated by interleukin-6 (IL-6), the major myeloma cell growth factor, or by other cytokines involved in multiple myeloma." (PMID 25071016, 2014). "In the case of co-culture with MSC, myeloma cells survive independent of the IL-6/gp130/STAT3 pathway suggesting that other pro-myeloma factors, such as CCN1, are provided by the stromal tumor microenvironment." (PMID 24965524, 2014). "It has previously been shown that survival of both INA-6 cells and primary myeloma cells is independent of IL-6 when cultured with MSC." (PMID 24965524, 2014). "When cultured in higher densities in medium supplemented by high FCS concentrations, MOPC315.BM myeloma cells did not require any external stimulation by APRIL or IL-6." (PMID 25272036, 2014). "There was no significant change in IL-6 secretion from multiple myeloma cells when PI3K/AKT, JNK, or MAPK pathways were inhibited." (PMID 24151609, 2013). "We found that some of myeloma cells including U266 cells showed stronger response to exogenous IL-6 (data not shown), and these cells also secreted more IL-6 in response to TNFα in vitro." (PMID 24151609, 2013). "Multiple myeloma patients also have decreased fibrinolytic activity because of increased PAI-1 (plasminogen activator inhibitor-1) activity, which is positively related to elevated IL-6 levels." (PMID 24151508, 2013). "Cytokines, such as IL-6, TGF-b, IL-10, and vascular endothelial growth factor (VEGF), which were actively produced by myeloma cells and were found to be in the tumor microenvironment as well as in the serum, played a role in preventing the development of functional DCs." (PMID 22649466, 2012). "Preclinical data suggest single-agent anti-myeloma activity for BPs (including zoledronic acid [ZOL]), as well as at least additive activity with anti-myeloma agents including thalidomide, dexamethasone and interleukin-6 antagonists in MM models." (PMID 21991938, 2012). "Thus, this study confirms that paracrine interactions between myeloma and marrow stromal cells triggered by VEGF and IL-6 represent feasible signal transduction pathways to target for treatment of MM." (PMID 20204067, 2010). "Both IL-6 and TNF-α have a proliferative effect on myeloma cells." (PMID 19191868, 2009). "There is little data, for example, to link cytokines important in the development of non-Gaucher multiple myeloma, such as IL-6, with multiple myeloma in Gaucher patients." (PMID 17655728, 2007). "For myeloma it is well known that interleukin-6 (IL-6) plays a crucial role in the cytokine network, regulating the growth and survival of myeloma cells and stimulating the acute-phase protein synthesis, notably C-reactive protein (CRP)." (PMID 16969356, 2006). "vIL-6 had activity on human myeloma cells, where exogenous application induced DNA synthesis and proliferation in the INA-6 myeloma cell line; this cell line is strictly dependent upon exogenous IL-6 for growth." (PMID 16138925, 2005). "Notably, IL-6 upregulates Mcl-1 expression through the JAK/STAT3 signaling pathway, which not only induces the proliferation and survival of multiple myeloma cells but also increases mitochondrial bioenergy production and confers protection against mitochondrial dysfunction in cortical neurons." (PMID 39272918, 2024). "It has been hypothesized that non-classical monocytes may produce cytokines such as IL-6 that may enhance myeloma cell growth." (PMID 37660077, 2023).
myeloma (continued). "Interestingly, CSF2 does not directly act as a growth factor in myeloma, but instead sensitizes cells to IL-6." (PMID 37250588, 2023). "However, IL-6 and IL-6R antibodies can block CSF3-induced myeloma cell proliferation." (PMID 37250588, 2023). "Moreover, the myeloma niche is immunosuppressive, as the activity of myeloid-derived suppressor cells (MDSCs), which secrete IL-10 and TGF-β, is enhanced by the production of IL-6, and granulocyte-macrophage colony-stimulating factor (GM-CSF) by MM cells." (PMID 36212502, 2022). "The proinflammatory cytokines (IL-6 and TNFα) secreted by CD169-positive TAMs are known to enhance vascular leakage and abrogate CD138-mediated cell adhesion; this may drive dissemination of myeloma cells into the blood circulation." (PMID 36547163, 2022). "However, cytokines such as IL-6 and VEGF can induce the activation of a variety of signaling pathways and promote cell adhesion-mediated drug resistance, thus promoting the proliferation of multiple myeloma cells and inhibiting cell apoptosis." (PMID 35813864, 2022). "IL-1b, TNF-a, IL-6, and IL-10 may contribute to osteopenia; IL-1b, TNF-a, and IL-6 may have a role in the activation of coagulation and hypermetabolism; IL-6 and IL-10 may be responsible for gammopathies and multiple myeloma." (PMID 36498496, 2022). "However, CaSR activators (such as Ca2+, NPS, R467) did not enhance IL-6 expression in these cells, indicating that CaSR agonists exerting a mitogenic effect on myeloma cells seemed to be independent of IL-6 actions." (PMID 34579758, 2021). "MSCs from myeloma patients (MM-MSCs) interrelate with MM cells and change the expression of certain angiogenic and growth factors (such as CD40/40L, VCAM-1, ICAM-1, LFA-3 and HO-1) and several cytokines (IL-6, IL-10 TGFb1, macrophage inflammatory protein-1b (MIP-1b) and IL-7)." (PMID 33923357, 2021). "Subgroup analysis showed that IL-6 rs1800795 SNP was significantly related to an increased possibility of cancer of breast, cervix, prostate, colon, and/or lung but not gastric cancer or multiple myeloma." (PMID 34327025, 2021). "IGF-1 is an endocrine factor produced and secreted by bone marrow stromal cells (BMSC), bone endothelial cells, and osteoblasts that promotes the homing, growth, and survival of myeloma cells in the bone marrow environment, both dependent and independent of IL-6." (PMID 33531904, 2021). "Finally, myeloma cells construct a feedback loop to ensure their own growth by producing CCL3 (MIP-1α), and increase OC activity in combination with RANKL and MIP-1α in synergy with IL-6 to promote their survival." (PMID 33806209, 2021). "Importantly, IL-6 is one of the mediators of dexamethasone resistance in myeloma cells via protein tyrosine phosphatase, nonreceptor type 11 (PTPN11, also known as SHP2)." (PMID 34067236, 2021). "OCs, in turn, also release several soluble factors (including IL6, CCL3, OPN, B-cell activating factor (BAFF), and a-proliferation-inducing ligand (APRIL)), which promote MM cell growth and survival, thus creating a vicious cycle between bone lesions and myeloma progression (see reviews)." (PMID 34067236, 2021). "IL6 is essential in multiple myeloma: cell lines that do not produce IL6 require exogenously added IL6, antisense IL6 strongly reduces proliferation and blocking the IL6R signaling pathways induces apoptosis while its constitutive activation confers resistance to apoptosis." (PMID 34359576, 2021). "Potential confounding by myeloma-derived inflammation has not been supported by correlations with indices of inflammation (interleukin-6 (Il-6) and C-reactive protein (CRP)), though circulating markers may not reflect local tissue levels." (PMID 32486490, 2020). "The regulatory function on IL-6 is observed only in MO-DCs but not in human myeloma cells." (PMID 32765503, 2020).
myeloma (continued). "In addition, upregulation of cytokines, such as IL-1, IL6, TNF-α, and hormones, such as PTHrp, increases RANKL expression and decreases OPG levels through the contact of plasma cells and stromal cells, and the myeloma microenvironment." (PMID 32937821, 2020). "Additionally, plasmacytoid dendritic cells (DCs), which are important in their role as APCs are often dysfunctional and release various soluble factors like VEGF, IL-6, SDF-1α among others upon interaction with MM cells, which in turn promote the growth and survival of myeloma cells." (PMID 32829378, 2020). "BZT also decreases adhesion of myeloma plasma cells to stromal cells and disrupts secretion of specific cytokines in the bone marrow microenvironment such as vascular endothelial growth factor (VEGF), insulin-like growth factor 1 (IGF-1), interleukin-6 (IL-6), and tumor necrosis factor-α (TNF-α)." (PMID 31979371, 2020). "In multiple myeloma patients, anti-IL6 antibodies did not prevent IL6 production." (PMID 33193322, 2020). "In this way, IL-6 could trigger the PI3K/Akt, NF-κB and MAPK/ERK signaling pathways in a manner similar to that observed in other tumors such as prostate cancer with the upregulation of cyclin A1, or bladder cancer and multiple myeloma." (PMID 29930760, 2018). "However, in small clinical trials regarding cancer, treatment with anti-IL6 or anti-IL6R has shown no clinical effect in patients multiple myeloma, metastatic renal cell cancer and castration-resistant prostate cancer." (PMID 30038723, 2018). "One possible explanation might be, that lenalidomide and pomalidomide not only activate the immune system, but also impact the malignant myeloma cell directly, and that IL-6 does not play a role in this mode of action." (PMID 29228683, 2017). "Hence, the IL-6-induced alternative splicing of the DCC locus probably leads to an impaired protein function and may contribute to myeloma cell survival." (PMID 28801664, 2017). "During the tumor progression of myeloma within the bone marrow, indeed, both interleukin (IL)-1α and IL-1β secreted by MM cells stimulate the stroma to produce IL-6 through the linkage of the early growth response (EGR)-1 protein to the promoter of IL-6 (pIL6)." (PMID 28962646, 2017). "Additionally, culture of human myeloma cell lines and primary cells with TLR ligands stimulates cell growth and spares these cells from serum deprivation or dexamethasone-induced apoptosis via autocrine secretion of interleukin-6 (IL-6)." (PMID 27733853, 2016). "In addition, IL-6 and FGF2 together can enhance proliferation of myeloma cells." (PMID 27007053, 2016). "Lack of anti-multiple myeloma effect of siltuximab in clinical trials could be explained by emergence of IL-6-independent subclones or substitution for IL-6 by other IL-6 family cytokines that utilize gp130 as a shared signal transducer." (PMID 26840088, 2016). "Beside the possible tumor autonomous production of IL-6, BMSCs represent the main source of IL-6 for myeloma cells, therefore we examined whether Notch signaling could affect the release of IL-6 from BMSCs." (PMID 27463014, 2016). "IL-6 could enhance c-Myc protein expression in multiple myeloma cells independent of any effect on Myc transcription." (PMID 26508814, 2015). "in response to IL-6 stimulation, immature but not mature myeloma cells proliferate markedly; 2)." (PMID 25781885, 2015). "The inhibitors were not potent in blocking secretion of IL-6 from U266 multiple myeloma cells." (PMID 24151609, 2013). "Anti-IL-6 antibodies emerge as a new therapeutic adjuvant option for patients attained of haematological cancers, as strengthened by preclinical works using anti-IL-6 antibodies with cis-diamminedichloroplatinium (CDDP) in RCC or melphalan in advanced multiple myeloma." (PMID 19956602, 2009). "Similarly, reduction in IL-6 and TNF-α levels could explain the action of lenalidomide in multiple myeloma." (PMID 19674465, 2009).